ROBO1 (roundabout guidance receptor 1)
Diseases named in the same sentence as ROBO1 in open-access papers (continued):
Sharing a sentence is not in itself a finding about the gene and the disease.
osteoporosis (1 paper, 2024). A condition of reduced bone mass, with decreased cortical thickness and a decrease in the number and size of the trabeculae of cancellous bone (but normal chemical composition), resulting in increased fracture incidence. "Consequently, ROBO1 emerge as a promising candidate for translational research in osteoporosis intervention based on osteoblast-mediated bone formation." (PMID 39439909, 2024). "Through the results of omics sequencing of clinical samples and screening of IMPC, this study successfully screened ROBO1 as a key molecule regulating osteoporosis, and ROBO1 downregulation may promotes osteoporosis by inhibiting osteoblast differentiation and mineralization." (PMID 39439909, 2024).
pancreatitis (1 paper, 2018). Inflammation of the pancreas. "Here we report that in pancreatitis and PDAC mouse models, epithelial Robo2 expression is lost while Robo1 expression becomes most prominent in the stroma." (PMID 30504844, 2018).
renal carcinoma (1 paper, 2020). A carcinoma arising from the epithelium of the renal parenchyma or the renal pelvis. "Previous studies have shown that ROBO1 is epigenetically silenced by promoter hypermethylation in breast, lung, and renal cancers." (PMID 32552834, 2020).
respiratory failure (1 paper, 2022). The significant impairment of gas exchange within the lungs resulting in hypoxia, hypercarbia, or both, to the extent that organ tissue perfusion is severely compromised. "Homozygous mice with targeted deletion in the Dutt1/Robo1 gene often die at birth due to respiratory failure, demonstrating delayed lung maturation and diaphragmatic defects in some instances." (PMID 35633948, 2022).
retinopathy of prematurity (1 paper, 2024). A bilateral retinopathy characterized by neovascularization, scarring, retinal detachment, and eventually blindness. "Data show significantly elevated expression levels of Robo1 in the retinas of mice with oxygen-induced retinopathy of prematurity." (PMID 39114443, 2024).
schistosomiasis (1 paper, 2023). An infectious disease caused by parasitic trematodes of the genus Schistosoma that colonize human blood vessels and release eggs that can cause granulomatous reactions leading to acute (swimmer's itch or acute schistosomiasis syndrome) or chronic disease. "The colocalization of Robo1 and HSCs was observed, particularly in the livers of patients with schistosomiasis." (PMID 37280619, 2023). "Taken together, these data demonstrated that miR-29a-3p upregulation reduced Robo1 expression and prevented schistosomiasis-induced HSC activation." (PMID 37280619, 2023). "Furthermore, miR-29a-3p overexpression significantly reduced Robo1 expression in activated HSCs and lessened schistosomiasis-induced HSC activation." (PMID 37280619, 2023). "Meanwhile, we examined the expression of Robo1 in control and schistosomiasis patients." (PMID 37280619, 2023). "In addition, we found significant correlations between the levels of miR-29a-3p and Robo1 and portal vein diameter and spleen thickness in patients with schistosomiasis." (PMID 37280619, 2023).
septal defects (1 paper, 2019). "This is the first study to find an association of SLIT2 and SLIT3 with predisposition to human CHD, although, of note, a recent study identified ROBO1 loss-of-function SNVs in cases with TOF and septal defects." (PMID 31613678, 2019).
sinus (1 paper, 2020). "In this study, we reconfirmed that endosomal release is necessary for saporin-conjugated anti-Robo1 antibody (IT-Robo1) in the cytotoxic effect against the Robo1-expressing maxillary sinus SCC cancer cells HSQ-89 using saponin." (PMID 32256588, 2020).
tongue cancer (1 paper, 2017). A malignant neoplasm affecting the tongue. "Additionally, ROBO1 effects on tongue carcinoma cells to enhance the ability of cell adhesion, invasion and migration by alerting the expression of matrix metalloproteinase and E-cadherin, which." (PMID 28977866, 2017).
Usher syndrome (1 paper, 2012). A syndromic diseae characterized by the association of sensorineural deafness (usually congenital) with retinitis pigmentosa and progressive vision loss. "Several of the top candidate genes include EEF1A1, ROBO1, PLXNA4, SLIT3, NRP1, and NOTCH2, as well as genes associated with the Usher syndrome, PCDH15 and USH2A, and are plausible candidates contributing to the developmental defects in Gbx2−/− mice." (PMID 23144817, 2012).
viral infection (1 paper, 2009). "The function for four targets have been ascribed (ROBO1, NLGN1, CPSF1, ATP8A1), but none of them have been linked with viral infection." (PMID 19788744, 2009).
tumor (129 papers, 2004 to 2025). "TCGA LGG and GBM datasets were evaluated separately to determine if rs4680975 genotype was associated with tumor expression of ROBO1 or ROBO2." (PMID 40709013, 2025). "The eQTL analyses demonstrated a significant association between the most significant variant (rs4680975) in this region and tumor expression of ROBO1." (PMID 40709013, 2025). "Tumor expression of ROBO1 was associated with rs4680975 genotype in IDHwt patients that have the rs55705857 risk allele (P = 0.034)." (PMID 40709013, 2025). "We also analyzed if reduced tumor growth observed in Robo1 knockout and Slit2‐treated SBC xenografts is linked to reduced angiogenesis." (PMID 35838343, 2023). "Taken together, these results suggested that ROBO1E280* is a loss-of-function mutation and represses the tumor suppressor function of ROBO1 in CCA." (PMID 35615148, 2022). "In vitro and in vivo experiments revealed that ROBO1 suppresses the proliferation and angiogenesis of CCA, while E280* nonsense mutation of ROBO1 loses the tumor-suppressing effects through interruption of the SLIT2/ROBO1 signaling pathway." (PMID 35615148, 2022). "SLIT2 interacts, with its cognate receptor ROBO1 in the human umbilical vein endothelial cells (HUVECs) and tumour-associated endothelial cells." (PMID 33318575, 2020). "By this interpretation, the most decreased expression in tumor protein relative to healthy tissue is in ROBO1 ∼72.3%, followed by delta sarcoglycan (encoded by SGCD) ∼68.9%, and syntrophin gamma 1 (SNTG1 gene) ∼58% (SGCD)." (PMID 29290962, 2017). "We observed a nonsense ROBO1 mutation as a potential tumor suppressor gene reported in other gastrointestinal tumors." (PMID 27009864, 2016). "Recently, this interaction has been shown to be implicated in tumor angiogenesis, where SLITs secreted from cancer cells act as attractants for ROBO1 expressing vascular endothelial cell migration." (PMID 24689049, 2014). "This is also the first study to show that the tumor-associated gene Robo1 is negatively regulated by miR-218 via a specific target site (nt 971–978) within the 3′-UTR." (PMID 20300657, 2010). "Additionally, we identified a deleterious nonsense mutation, ROBO1E280*, in CCA, which loses the tumor-suppressing function of wild-type ROBO1 due to its translocation and interruption of the SLIT2/ROBO1 signal pathway." (PMID 35615148, 2022). "However, the role of the genetic variants on the interaction of SLIT2/ROBO1/4, potentially altering the anti-angiogenic pathway and overall tumour suppressive function, is yet to be elucidated." (PMID 33318575, 2020). "Robo1 has also been functionally implicated in the vasculature and in the context of tumor growth." (PMID 28973045, 2017). "In contrast, other studies have argued that the downregulation of Robo1 caused by deletions or epigenetic modifications may play a role in tumor progression." (PMID 20300657, 2010). "Mechanistically, SLIT2 promotes microglia/macrophage chemotaxis and tumor‐supportive polarization via roundabout guidance receptor 1/2 (ROBO1/2)‐mediated PI3Kγ activation in macrophages." (PMID 40843131, 2025). "SLIT2 slows growth, while ROBO1 promotes it, by regulating the TGF-β1/GSK3-β/β-catenin signaling pathway in tumor cells and tumor-associated macrophages (TAMs)." (PMID 41217667, 2025). "Subsequently, we treated these primary tumor cells and tumor organoids with ROBO1-NK and observed a high efficacy of ROBO1-NK in effectively eliminating these targets." (PMID 39069888, 2024). "It was found that ROBO1-NK cells exhibited similar cytotoxicity against tumor cells as normal NK cells." (PMID 39069888, 2024). "To correspond with the translational focus of this investigation, we employed patient tumor organoids as our ex vivo model to extend our investigation into the lysing potential of ROBO1-NK cells." (PMID 39069888, 2024). "After 48 h, ROBO1-NK cells almost completely eradicated the spindle-type primary tumor cells, whereas PBMC-NK cells left some residual cells." (PMID 39069888, 2024).
tumor (continued). "The clinical samples positive for ROBO1 reinforced the high anti-tumor potential of ROBO1-NK cells, highlighting their proficient targeting ability." (PMID 39069888, 2024). "Remarkably, the findings of this investigation underscored the remarkable efficacy of ROBO1-NK cells in selectively eliminating tumor cells and organoids." (PMID 39069888, 2024). "The secretion of Slit2 by tumor cells attracts Robo1 present in endothelial cells to migrate towards the tumor, inducing new blood vessel formation." (PMID 39456164, 2024). "Tissues showing positive ROBO1 expression were used to establish primary tumor cells and tumor organoids." (PMID 39069888, 2024). "It has been observed that ROBO1 is highly expressed in tumor cells, and the SLIT-ROBO signaling pathway plays a pivotal role in tumor angiogenesis and metastatic processes." (PMID 39069888, 2024). "SLIT2 has been identified as a tumor suppressor gene in SCLC, with its expression significantly reduced in this type of tumor, while ROBO1 expression is significantly higher in SCLC cells compared to adjacent normal cells." (PMID 38983267, 2024). "In precancerous intestinal lesions and during tumor progression, Slit2/Robo1 signaling triggers the Wnt/β-catenin pathway by down-regulating E-cadherin and induces EMT." (PMID 38081962, 2024). "This dual function of ROBO1 lays a mechanistic foundation for its selective pressure in metastatic tumour-host coadaptation." (PMID 36792623, 2023). "The results illustrated high ROBO1 expression in most liver metastasis tissues, even if the positive rate was much lower in matched primary tumours." (PMID 36792623, 2023). "Then, tumour cells expressing Robo1-FL or ΔRobo1 were intrasplenically injected into mice to further investigate the role of ROBO1 in liver metastasis." (PMID 36792623, 2023). "Flow cytometry analysis demonstrated an increase in Panc02Robo1-FL cells in the population from PG0 to PG2 in the tumour cell mixture, indicating that ROBO1 facilitated the survival and outgrowth ability of tumour cells for selection in the liver." (PMID 36792623, 2023). "Here the authors show that hepatoctyes overexpress SLIT2 to enable premetastatic niche formation for ROBO1-positive PDAC cells to support the survival of these tumour cells in the liver." (PMID 36792623, 2023). "To elucidate the molecular mechanisms used by the Slit2/Robo1 pathway to regulate tumor growth, we performed RNA sequencing on SBC5‐Robo1 KO and SBC5‐Scr cells." (PMID 35838343, 2023). "In summary, our results for the first time, establish a tumor‐suppressive role of Slit2 and tumor‐promoting role of Robo1 in SCLC." (PMID 35838343, 2023). "We also find that hepatocyte-derived SLIT2 forms a supportive environment for the implantation of ROBO1-positive DTCs, thus triggering coadaptation of hepatocytes and tumour cells to further support the development of the MMN." (PMID 36792623, 2023). "Tumor initiating function of Robo1 is also evident in the development of bronchial epithelial hyperplasia and focal dysplasia in Robo1 knockout mice." (PMID 35838343, 2023). "Using genetically engineered SCLC cells, adenovirus gene therapy, and preclinical xenograft models, we show that SLIT2 overexpression or the deletion of ROBO1 restricts tumor growth in vitro and in vivo." (PMID 35838343, 2023). "The results revealed that administration of the neutralizing antibody sufficiently retarded the progression of metastasis mediated by Robo1-FL-expressing tumour cells." (PMID 36792623, 2023). "Mechanistic studies showed that the Slit2/Robo1 signaling prevents the polarization of pro‐tumor M2‐like macrophages in the tumor microenvironment (TME) by targeting Tgf‐β1 signaling." (PMID 35838343, 2023). "Slit2 tumor‐suppressor activity acts primarily through Robo1, as the treatment of Robo1−/− SCLC with rSlit2 protein, does not further inhibit the tumorigenic properties of these cells." (PMID 35838343, 2023).
tumor (continued). "The SLIT2-rich liver microenvironment not only supported the survival and outgrowth of disseminated ROBO1+ tumour cells but also exerted selective pressure on DTCs to enrich ROBO1+ cells." (PMID 36792623, 2023). "Molecular analysis showed that ROBO1 knockout or SLIT2 overexpression suppresses the transforming growth factor beta 1 (TGF‐β1)/β‐catenin signaling pathway in both tumor cells and macrophages." (PMID 35838343, 2023). "And both down-regulation of SLIT2 expression and over-expression of ROBO1 can promote tumor growth and metastasis." (PMID 37059586, 2023). "Knockdown of ROBO1 in the human cell line PANC1 significantly decreased the tumour burden in a liver metastasis mouse model." (PMID 36792623, 2023). "Despite the initial tumor size being similar, xenografts bearing miR-588-U87MG cells exhibited tumor growth inhibition and longer survival times than control group, whereas overexpression of ROBO1 inhibited the effect of miR-588 in vivo." (PMID 36459288, 2023). "Molecular analysis showed that SLIT2 overexpression or ROBO1 deletion suppresses the transforming growth factor‐beta 1 (TGF‐β1)/β‐catenin signaling pathway in both tumor cells and macrophages." (PMID 35838343, 2023). "Tumour cells expressing full-length ROBO1 protein (Kpc1199Robo1-FL or Panc02Robo1-FL) were intrasplenically implanted into Slit2 fl/fl (CTRL), CKO and CKO-RE mice." (PMID 36792623, 2023). "Consistently, overexpression of SLIT2 in CAPAN-1 cells derived from human PDAC liver metastases with a high level of ROBO1 expression increased the tumour burden." (PMID 36792623, 2023). "On the other side, decreased expression of tumor suppressor miRNAs, such as miR-218 and let-7, promote tumor invasiveness in GC by eliminating repression of the Robo1 pathway and increasing high mobility group AT-hook 2 (HGMB2) expression, respectively." (PMID 37371856, 2023). "In the CKO-RE group, the paracrine resumption of SLIT2 expression by hepatocytes restored the outgrowth ability of Robo1-FL-expressing tumour cells." (PMID 36792623, 2023). "For example, miR-490-5P and miR-152-3P act as tumor suppressors and can be used to target ROBO1 in hepatic tumorigenesis." (PMID 37238655, 2023). "Previous studies showed that ROBO1 increases PC cell proliferation, migration, and invasion and thereby promotes tumor growth." (PMID 36277474, 2022). "On the contrary, several studies have shown that the SLIT2/ROBO1 signal suppresses neovascular formation, especially in tumor angiogenesis." (PMID 35615148, 2022). "In the study, we confirmed ROBO1 as a tumor suppressor in CCA patients and that the downregulation of ROBO1 is correlated with poor prognosis." (PMID 35615148, 2022). "It has been reported that ROBO1 plays an important role in cancer invasion, migration, epithelial–mesenchymal transition and tumor-induced angiogenesis through SLIT2/ROBO1 signaling." (PMID 36498797, 2022). "For example, the enhancement of ROBO1 expression triggers tumour growth, invasion and metastasis in HCC Sk-hep-1 cells." (PMID 35236289, 2022). "While an unregulated level of ROBO1 expression in PC tumor stroma was found to support tumor invasiveness and metastasis, ROBO1 overexpression in PC cells (PANC-1 and MiaPaca-2) was found to reduce cell proliferation, suggesting a tumor suppressive effect." (PMID 36277474, 2022). "The convertible role of ROBO1 as a tumour suppressor or an oncogene has been observed in different cancer types." (PMID 35236289, 2022). "Compared with non-tumour tissues, the elevation of ROBO1 and the reduction of miR-152-3p were observed in HCC tissues." (PMID 35236289, 2022). "Endothelial-derived SLIT2 protein and its receptor ROBO1 reportedly promote the migration and infiltration of cancer cells into endothelial tissue, whereas endothelial Slit2 knockout can inhibit tumor metastasis." (PMID 36172371, 2022). "The results showed that ROBO1 overexpression significantly inhibited tumor growth in vivo, which was partially reversed by ROBO1E280*." (PMID 35615148, 2022).